POTEB2 (POTE ankyrin domain family member B2)
Tractability: PROTAC: ubiquitination databases record sites on it.
Gene: Protein-coding gene on chromosome 15 (20,835,372 to 20,866,314, reverse strand). Ensembl gene ENSG00000230031.
Homologues: Paralogues in human: POTEB (100% identical), POTEB3 (99% identical), POTED (95% identical), POTEC (89% identical), POTEI (87% identical), POTEJ (87% identical), POTEF (87% identical), POTEE (87% identical), POTEH (77% identical), POTEG (77% identical), POTEM (77% identical), POTEA (60% identical), and 2 more.